TLR4 (toll like receptor 4)
Diseases named in the same sentence as TLR4 in open-access papers (continued):
Sharing a sentence is not in itself a finding about the gene and the disease.
Insulin resistance (continued). "This endotoxemia stimulating toll-like receptor 4 (TLR4) receptor and its cofactor cluster of differentiation 14 (CD14) have established the link between the gut of obese patients and their insulin resistance state which is a central feature of the metabolic syndrome." (PMID 36078124, 2022). "In summary, TLR4 inhibition with eritoran did not improve glucose metabolism parameters in humans, which does not support a role for TLR4 in insulin resistance." (PMID 36066991, 2022). "TLR4 signaling leads to the activation of the NFκB pathway, which results in the secretion of inflammatory mediators (e.g., TNFα, MCP-1, and IL-6) and stimulates insulin resistance." (PMID 35889783, 2022). "On the other hand, during an acute challenge with saturated fatty acids, a negative role of TLR4 as a mediator of insulin resistance in the adipocytes was observed." (PMID 34327205, 2021). "Saturated fatty acids trigger insulin resistance by activating TLR-2 and TLR-4." (PMID 34832960, 2021). "By binding to the Toll-like receptor-4 (TLR-4)–CD14 complex, Lipopolysaccharide (LPS) activates the immune system, interfering with the insulin receptor and leading to an increase in testosterone production resulting in PCOS and insulin resistance." (PMID 34357331, 2021). "Overall, the present investigation demonstrates that calystegines from Hyoscyamus albus provide cytoprotection to the HepG2 cells against insulin/glucose induced insulin resistance and apoptosis due to the regulation of SIRT1/Foxo1/G6PC/mTOR and NF-κB/JNK/TLR4 signaling pathways." (PMID 34034759, 2021). "Dysbiosis can impair the function of the intestinal barrier to allow the passage of LPS from intestinal Gram-negative bacteria into the systemic circulation, which can stimulate Toll-like receptor 4 (TLR4)-mediated inflammation, leading to metabolic endotoxemia and insulin resistance." (PMID 35046924, 2021). "JZG may regulate CD14/TLR4 and TLR2 signaling pathways, improving inflammation and insulin resistance targeted at gut microflora." (PMID 34966475, 2021). "Insulin resistance in skeletal muscles from nonobese patients with impaired glucose tolerance is mainly mediated by upregulation of TLR4 due to increased IL-6-mediated STAT3 activation." (PMID 33376487, 2020). "Conversely, a study demonstrated that total body TLR4 knockout or the deletion of TLR4 in non-hematopoietic or hematopoietic cells further enhanced insulin resistance." (PMID 32947825, 2020). "The Toll-like receptor 4 (TLR4) signaling pathway induces the production of proinflammatory cytokines by regulating the activities of c-Jun N-terminal kinase (JNK) and NF-κB, and leads to chronic inflammation and insulin resistance." (PMID 33551809, 2020). "TLR4 activates downstream NF‐κB signaling to increases the synthesis and secretion of MCP1, which promotes macrophage recruitment to adipose tissue and the development of insulin resistance 27-29." (PMID 33162789, 2020). "In summary, our results show that high glucose administration results in glucose intolerance with insulin resistance through impairment of GLP-1 secretion, elevated level of blood glucose, activation of TLR4 and subsequently increased levels of IL-6 and TNF-α in mice." (PMID 31138952, 2019). "Accordingly, recent studies reported that genetic disruption of key inflammatory pathways in the hypothalamus, such as TLR4/MyD88 or IKKb/NF-kB pathways, is protective against the metabolic complications induced by HFD including hypothalamic insulin resistance." (PMID 30906281, 2019). "In addition, circulating FAs bind to toll-like receptor 4 (TLR4), thereby triggering enhanced synthesis of CERs leading to insulin resistance via the activation of inflammatory pathways." (PMID 30909521, 2019).
Insulin resistance (continued). "This process leads to impaired gut barrier integrity and release of LPS from intestinal gram-negative bacteria into the bloodstream which in turn leads to Toll-like receptor 4 (TLR4)-mediated metabolic endotoxemia (ME), LGCI and insulin resistance in obese mice." (PMID 30424806, 2018). "Interestingly, TLR4 gene expression and protein levels seem to be significantly upregulated in T2DM, eventually leading to insulin resistance." (PMID 29922174, 2018). "Supporting this hypothesis is the finding that TLR4-mutant mice were resistant to hepatic steatosis, induction of TNF-α, lipid peroxidation, and insulin resistance compared with wild type mice." (PMID 29983886, 2018). "IL-1β is a ligand for the IL-1 receptor which, like TLR4, signals via MyD88, IL-1 receptor-activated kinases (IRAK1 to 4), IKK, and NF-κB and should thus potentiate the whole model for insulin resistance in insulin target cells." (PMID 30116482, 2018). "In fact, RBP4 has been shown to play a role in TLR4-mediated inflammatory signaling and insulin resistance independent of STRA6." (PMID 28689994, 2017). "In summary, our results demonstrate that ectopic expression of constitutively active TLR4 driven by aP2 promoter induces inflammation in white adipose tissue; however, it does not induce systemic insulin resistance." (PMID 28776958, 2017). "Molecular links leading to TLR4-induced insulin resistance are not fully elucidated, but some studies mention that TLR4 signaling interferes with insulin signaling." (PMID 27105827, 2016). "The importance of metabolic endotoxemia in the physiopathology of insulin resistance and obesity has been further highlighted by Shi and colleagues, who showed that mice lacking TLR4 were protected against insulin resistance induced by a high-fat diet." (PMID 27098727, 2016). "A study demonstrating the anti-inflammatory properties of n-3 PUFA via suppression of toll-like receptor 4 (TLR4) activation in muscle reported improvements in inflammatory markers (TNFα, CRP, IL-6) and insulin resistance as measured from oral glucose and insulin tolerance tests (OGTT and ITT)." (PMID 27258299, 2016). "Moreover, SCFA and bacterial lipopolysaccharides activate Toll-Like receptor 4 (TLR4) and signal intracellular inflammatory pathways related to the induction of insulin resistance and increased adiposity." (PMID 26925392, 2016). "Indeed, it has been suggested that activation of TLR4 signaling directly alters the phosphorylation status of IRS, which in turn impairs AKT activation and thus induces insulin resistance in adipose tissue." (PMID 26539824, 2015). "While increased muscle Tlr-4 expression has been shown to contribute to insulin resistance, no insulin resistance was present after 3 weeks of HFD when Tlr-4 was upregulated." (PMID 23951235, 2013). "Another report showed that TLR4 signaling is not directly required for saturated or unsaturated fat-induced hepatic insulin resistance in mouse models." (PMID 24064574, 2013). "The insulin resistance in TLR2 KO mice could be explained by the increased LPS serum levels, which lead to TLR4 activation in the insulin target organs." (PMID 24064574, 2013). "Our data suggest that metabolic endotoxemia could be involved in the pathogenesis of insulin resistance in obese and T2DM subjects and that targeting TLR4 might be beneficial in these individuals." (PMID 23704966, 2013). "Although numerous studies have demonstrated that TLR2- and TLR4-dependent signaling are involved in the development of insulin resistance, data on a similar mechanism in the pathogenesis of insulin resistance in RA patients are still lacking." (PMID 23213270, 2012). "Further, clarification is needed for the respective contribution of TLR4 signaling in hematopoietic vs. non-hematopoietic compartment to the development of insulin resistance." (PMID 23316186, 2012).
Insulin resistance (continued). "Although the mechanisms by which alterations in the TLR4 signaling cascade can lead to insulin resistance and type II diabetes is not known, it is becoming increasingly apparent that it plays a role in the susceptibility." (PMID 22970372, 2012). "Well controlled studies by several investigators offered strong evidence that saturated fat diet-induced insulin resistance was blunted in mice that lacked functional TLR4." (PMID 21314942, 2011). "Our increasing understanding of TLR4 and insulin resistance will facilitate the design of novel therapeutic approaches that can derail the negative metabolic effects of TLR4 activation from the important functions of innate immunity." (PMID 20814545, 2010). "This corroborates a previous in vivo study, where C57BL/6 mice lacking TLR4 (TLR4-knockout, TLR4−/− mice) were partially protected from high-fat diet-induced insulin resistance, suggesting that TLR4 acts as molecular link among pro-inflammatory responses, nutrition, and lipids." (PMID 40910216, 2025). "Recent human experiment of eritoran (a TLR4 antagonist) failed to improve insulin resistance, suggesting that simple blockade might be insufficient." (PMID 41459531, 2025). "However, the relevance of the effect of TLR2 and TLR4 on conditions such as insulin resistance is not entirely clear, with some studies indicating that TLR2 is a protective factor and others indicating the opposite." (PMID 40076851, 2025). "In an animal study, it was shown that the activation of TLR4 in rats is inhibited by a high dietary omega-6/omega-3 PUFA ratio, which in turn reduces their circulating lipid concentrations, improves their glucose tolerance, and ameliorates their insulin resistance." (PMID 39086538, 2024). "Unexpectedly, targeted loss of function of NCoR in macrophages resulted in protection from diet-induced insulin resistance and an attenuated, rather than exaggerated, transcriptional response to the Toll-like receptor 4 (TLR4) agonist, lipopolysaccharide (LPS)." (PMID 38165941, 2024). "Moreover, animals lacking TLR4 were protected against insulin resistance generated by a high-fat diet." (PMID 36674680, 2023). "Acute TLR4 inhibition with eritoran did not protect against lipid-induced insulin resistance." (PMID 36066991, 2022). "Mechanisms by which lipids induce insulin resistance may be independent of TLR4, such as intracellular accumulation of lipid metabolites." (PMID 36066991, 2022). "Knockdown of protein kinase C theta in the ARC or toll-like receptor 4 (TLR4)-adaptor molecule, MyD88, in the CNS prevented HFD- or ICV palmitate-induced weight gain and insulin resistance, highlighting some of the mechanisms of palmitate-induced central insulin resistance." (PMID 34831343, 2021). "Results of our own and other groups suggest that intestinal barrier dysfunction and subsequently an increased translocation of bacterial endotoxin and induction of TLR4-dependent signaling cascades may be critical in the onset and progression of both NAFLD and insulin resistance." (PMID 33809593, 2021). "Interestingly, different rodent models of TLR4 ablation, either genetically modified by knock-out approaches or by pharmacological inhibition, have shown to prevent HFD-induced insulin resistance." (PMID 33967682, 2021). "However, the mechanism by which TLR4 mediates inflammation and insulin resistance is probably not fully understood." (PMID 33013197, 2020). "Since these studies used total body knockout or mutant mice, it was not clear whether it was TLR4 on hematopoietic cells or in the AT that promoted the development of insulin resistance." (PMID 32947825, 2020). "The binding of LPS with TLR4 could result in the stimulation of IKKβ and NF-κB and then increase the levels of downstream inflammatory factors (like TNF-α, IL-6, IL-1β, etc.), which promoted the insulin resistance in the tissue where they were produced." (PMID 30210342, 2018).
Insulin resistance (continued). "Interestingly, fetuin-A was identified as an adaptor protein for saturated fatty acid-mediated activation of Toll-like receptor 4 (TLR4), which may integrate insulin resistance and inflammatory signaling." (PMID 30675162, 2018). "Based on the two transgenic lines that were generated and characterized, we found that aP2‐driven expression of constitutively active TLR4 was not sufficient to induce systemic insulin resistance, despite being sufficient to induce elevated inflammation in WAT." (PMID 28776958, 2017). "The mechanism may involve TLR4 activation in macrophages as it was shown that TLR4 requires STAT4 for IFNγ production in response to IL12 and ablation of TLR4 in the myeloid compartment prevents insulin resistance in obese mice." (PMID 28400678, 2017). "Therefore, our findings imply that endocytosis of TLR4 and NOX2 could be a novel therapeutic target for NAFLD, including hepatic steatosis and insulin resistance." (PMID 29269727, 2017). "Interestingly, Tlr4−/− mice have lower expression of pro-inflammatory markers such as TNF-α and IL-6 and are protected from insulin resistance, emphasizing that inflammation may affect metabolism." (PMID 27617199, 2016). "Activation of TLR4, another receptor of HMGB-1, activated proinflammatory kinases (such as p38MAPK and JNK) that impaired insulin signal transduction via inhibitory phosphorylation of insulin receptor substrate, suggesting the involvement of HMGB-1 in insulin resistance." (PMID 27847406, 2016). "However, myeloid/haematopoietic cell-specific TLR4 knockout mice as generated by adoptive BM transfer were not protected from HFD-induced skeletal muscle insulin resistance, whereas hepatic insulin sensitivity was significantly improved." (PMID 24203314, 2014). "Therefore, RP105 or MD-1 KO mice may impair both TLR4- and TLR2-mediated promotion of adipose tissue inflammation and insulin resistance." (PMID 24064574, 2013). "Thus, we have found that the insulin resistance presented by TLR2 KO mice could be explained by the increased LPS serum levels, which led to increased activation of TLR4 in muscle, liver and adipose tissue, and increased phosphorylation of JNK, but not of IKK." (PMID 23482058, 2013). "Therefore, it is difficult to accurately assess the effect of TLR4 (or lack of TLR4) on insulin resistance/inflammation in a model where adiposity is not equal." (PMID 21314942, 2011). "However, contrary to our hypothesis, TLR4 inhibition with eritoran did not prevent lipid-induced insulin resistance." (PMID 36066991, 2022). "TLR4 may be the trigger of metabolite-mediated Kupffer cells activation, which plays critical role in the pathogenesis of high fat-induced inflammation and insulin resistance, but the detailed mechanism is probably not fully understood." (PMID 33013197, 2020). "However, DAG-PKC-induced insulin resistance without TLR4 activation has also been reported." (PMID 30116482, 2018). "Together, these results suggest that constitutively active TLR4‐induced inflammation in white adipose tissue is not sufficient to induce systemic insulin resistance, and that high fat diet‐induced insulin resistance may require other signals in addition to TLR4‐mediated inflammation." (PMID 28776958, 2017). "Interestingly, the activation of TLR4, one of the best known TLR member, expressed in several tissue cells, such as cells of the pancreatic islets (i.e., β-cells and resident macrophages), can induce both insulin resistance, pancreatic β-cell dysfunction, and alteration of glucose homeostasis." (PMID 24803744, 2014). "It has been hypothesized that peripheral insulin resistance is augmented by stimulation of intestinal Toll-like receptor 4 (TLR4) primarily by LPS from Gram-negative Proteobacteria leading to secretion of proinflammatory cytokines such as tumor necrosis factor alpha (TNFα)." (PMID 24369539, 2013).
Insulin resistance (continued). "Therefore, it is likely that ER stress and insulin resistance observed in WT and not in TLR4−/− mice after HFD is mostly due the fat content of the diet even if we may not rule out a partial indirect contribution of sucrose." (PMID 23741455, 2013). "More recently, hepatocyte-specific targeting of TLR4 ameliorated hepatic steatosis and improved insulin resistance but did not affect weight, while macrophage-specific targeting of TLR4 did not protect mice from DIO, insulin resistance or hepatic steatosis." (PMID 35474339, 2022). "The siRNA-mediated reduction in TLR4, but not TLR2, in livers of LKO mice significantly ameliorated the insulin resistance." (PMID 24614850, 2014). "Intriguingly, high-glucose load failed to impair glucose tolerance and did not change the levels of plasma IL-6 and TNF-α in TLR4 knockout mice, which suggests a critical role of TLR4 in increase of IL-6 and TNF-α levels and glucose intolerance and insulin resistance induced by high-glucose load." (PMID 31138952, 2019).